ICAM1 (intercellular adhesion molecule 1)
Diseases named in the same sentence as ICAM1 in open-access papers (continued):
Sharing a sentence is not in itself a finding about the gene and the disease.
cholestasis (6 papers, 2017 to 2024). Impairment of the bile flow caused by obstruction within the liver, or outside the liver in the bile duct system. "In addition, several genes were significantly downregulated at the highest dosage and classified into different functional groups; Abcb1a and Icam1 are associated with cholestasis." (PMID 28533734, 2017). "Various molecules such as CCL2, CXCL1, CXCL2, and ICAM-1 have been reported to be important in neutrophil trafficking in the liver, which explains why liver injury occurs during cholestasis." (PMID 32701506, 2020). "However, when a similar approach was used in the LCA cholestatic mice, employing intercellular adhesion molecule-1 (ICAM-1) deficient mice (that do not express this protein fundamental for neutrophil toxicity), cholestasis was not affected by reduction in neutrophil activity." (PMID 31014010, 2019).
chondrosarcoma (6 papers, 2010 to 2023). A malignant cartilaginous matrix-producing mesenchymal neoplasm arising from the bone and soft tissue. "The third most up-regulated gene after IL-1β was ICAM1, which is a cell adhesion molecule that was recently associated with cell motility and migration of chondrosarcoma cells." (PMID 24901233, 2014). "rCCN6 enhanced migration of the human chondrosarcoma cell line JJ012 by increasing intercellular adhesion molecule 1 (ICAM-1) expression via αvβ3 and αvβ3 integrins, FAK and MAPK signaling." (PMID 29361725, 2018). "Our experimental data have shown that CCN6 enhances the wound-healing migration of chondrosarcoma cells by increasing ICAM-1 expression." (PMID 30237403, 2018). "Our previous work indicates that CCN6 regulates metastasis in chondrosarcoma, enhancing chondrosarcoma cell migration by increasing levels of ICAM-1 expression." (PMID 30237403, 2018). "We previous reported WISP-3 promoted chondrosarcoma migration through upregulated ICAM-1 production." (PMID 28465477, 2017). "However, we have previously indicated that WISP-3 promotes human chondrosarcoma migration through activation of intercellular adhesion molecule-1, which implies that WISP-3 mediates metastasis in chondrosarcoma." (PMID 28465477, 2017). "Here, we show that other genes under NF-κB control, such as IL-6, IL-8, ICAM-1 and Mcp-1, are modulated as well in the HTB-94 chondrosarcoma cell line stimulated with TNFα." (PMID 20113495, 2010).
coagulation disorders (6 papers, 2011 to 2025). "These seven markers were: Pentraxin-3 (‘disturbed vasculogenesis’), VCAM-1 and ICAM-1 (both EC Activation), Thrombomodulin (‘coagulopathy’), MCP-1, IP-10 and VEGF (all ‘disturbed angiogenesis’)." (PMID 37194071, 2023). "Third, we only determined serum thrombomodulin levels and we did not analyze other biomarkers of coagulopathy or vascular injury such as protein C, protein S, ICAM-1, VCAM-1 and E-selectin." (PMID 28771554, 2017).
edema (6 papers, 2017 to 2024). An abnormal accumulation of fluid beneath the skin, or in one or more cavities of the body. "ICAM-1 is responsible for the binding and extravasation of granulocytes, which result in the formation of pulmonary oedema and local inflammation." (PMID 35625767, 2022).
eosinophilia (6 papers, 2013 to 2022). "Anti-ICAM-1-treated mice showed lower lung ILC2s, lower BAL eosinophilia associated with a decrease in ILC2-dependent IL-5 and IL-13 expression compared to controls." (PMID 33193309, 2020). "Thus, several possible biomarkers have been described, either blood (IL, biliary acids, TNF, ICAM-1, hialuronic acid, eosinophilia, B2-microblobulin) or biliary markers (IL-2, IL-6, ICAM-1, cellularity changes)." (PMID 25489845, 2014). "ICAM-1, VCAM-1) and tissue eosinophilia in both the upper and lower airway." (PMID 33376573, 2020). "Complete abrogation of eosinophilia was observed in ICAM-1/VCAM-1 double KO mice after allergen challenge, demonstrating the direct regulation of endothelial-eosinophil interactions governing eosinophilia." (PMID 23378838, 2013).
Glomerular sclerosis (6 papers, 2013 to 2023). Accumulation of scar tissue within the glomerulus. "RAGE vaccination in db/db mice attenuated urinary albumin excretion, podocyte injury, and glomerular sclerosis, as well as reduced ICAM–1 and VCAM–1 production." (PMID 37007029, 2023).
Granuloma (6 papers, 2011 to 2024). A compact, organized collection of mature mononuclear phagocytes, which may be but is not necessarily accompanied by accessory features such as necrosis. "As the level of soluble ICAM-1 in bronchoalveolar lavage is reportedly correlated with the severity of sarcoidosis, ICAM-1 expression in monocytic cells seems to have some association with granuloma formation." (PMID 33923123, 2021). "ICAM-1 is found at elevated levels within egg-evoked granulomas and TNF-α drives the host immune response to schistosome eggs." (PMID 30059006, 2018). "Parenteral injection of tolerated proteins into orally tolerant mice blocked the increase of pulmonary granulomas and the expression of ICAM-1 in lung parenchyma in areas outside the granulomas." (PMID 22013486, 2012). "Our results show that the majority of S. mansoni egg-induced ICAM-1 expression 18 days after pulmonary granuloma induction was restricted to the lung parenchyma outside the granulomas." (PMID 22013486, 2012). "In schistosomiasis, expression of ICAM-1 and its cognate integrin are strongly upregulated and are used by schistosome eggs to adhere to the endothelium of the liver where they eventually form granulomas in the affected patient." (PMID 39739969, 2024). "Thus, our results identified elevated expression of ICAM-1 and leptin in serum and granulomas of sarcoidosis patients." (PMID 26368286, 2015). "We compared granulomas size from day 1 to day 18 after i.v. eggs, granuloma cellular composition, spleen, lung and serum cytokines levels, and the expression of intercellular adhesion molecule-1 (ICAM-1) in the lung." (PMID 22013486, 2012). "However, in the lung parenchyma outside granulomas, the expression of ICAM-1 was significantly inhibited in the tolerant mice." (PMID 22013486, 2012). "Therefore, elevated serum ICAM-1 levels may be responsible for inflammation and the formation of granulomas, which we will investigate in our future studies." (PMID 26368286, 2015).
kidney injury (6 papers, 2018 to 2022). Trauma to the kidney. "Authors showed significantly attenuated expression of NF-κB messenger RNA, inhibiting overactivation of NF-κB and further reducing the generation of tumor necrosis factor (TNF)-α and ICAM-1 by MSCs in an inflammatory mouse model of kidney injury." (PMID 32843073, 2020). "Our data show that five inflammation markers (TNF-α, TNFR1, TNFR2, ICAM-1, and adiponectin) also correlated with the extent of kidney injury in African American men, as determined by the UACR." (PMID 30868076, 2019). "Moreover, physiologic concentrations of NO inhibit expression of ICAM-1 and aggregation of macrophage/monocyte, while higher concentrations of NO can worsen kidney injury." (PMID 32952945, 2020). "A S1PR1 agonist, SEW2871, also ameliorated I/R kidney injury by reducing the infiltration of neutrophils/macrophages and proinflammatory molecules (TNF-α, P-selectin, E-selectin and intercellular adhesion molecule-1; ICAM-1)." (PMID 35409370, 2022). "Furthermore, consistent with a previous finding in the mouse model with acute kidney injury, overexpression of Klf4 also inhibited adhesion cytokines, including VCAM‐1 and ICAM‐1 (P < .05)." (PMID 31800161, 2020). "Indeed, urinary ICAM-1, plasma TNF-α, and adiponectin had moderate positive correlations with UACR while plasma TNFR1 and TNFR2 levels were strongly correlated with kidney injury, indicated by multiple biomarkers of kidney injury." (PMID 30868076, 2019).
leptospirosis (6 papers, 2014 to 2021). A contagious bacterial infection caused by spirochetes of the genus Leptospira. "Few studies attempt to investigate the value of biomarkers such as syndecan-1, intercellular adhesion molecule-1, neutrophil gelatinase-associated lipocalin, and defensinα1 in leptospirosis-associated AKI." (PMID 34124239, 2021). "This study shows that two adhesion molecules, shed as soluble forms, are elevated during the acute phase of leptospirosis: E-selectin and s-ICAM1." (PMID 28686648, 2017).
metastasis (6 papers, 2015 to 2023). The spread or migration of cancer cells from one part of the body (where they first appeared) to another. "In line with this notion, the incidence of lymph node or liver metastasis was significantly lower in patients with ICAM-1-positive colorectal tumors than in those with ICAM-1-negative tumors." (PMID 26513172, 2015).
nasopharyngeal carcinoma (6 papers, 1999 to 2024). A carcinoma arising from the nasopharyngeal epithelium. "In nasopharyngeal carcinoma, exosomes are highly enriched in intercellular adhesion molecule-1 (ICAM-1), CD44 variant isoform 5 (CD44v5) and matrix metalloproteinase 13 (MMP-13), in contrast, angio-suppressive protein TSP-1 is downregulated in these exosomes." (PMID 38200509, 2024). "Chan's team discovered that EVs derived from nasopharyngeal carcinoma (NPC) cells exhibited high levels of ICAM-1 and CD44 variant 5 (CD44v5) expression." (PMID 37735659, 2023). "Similarly, nasopharyngeal cancer-derived EVs contained intercellular adhesion molecule-1 (ICAM-1) and CD44 variant isoform 5 (CD44v5), which significantly increase the migration, invasion, and tubulogenesis of endothelial cells." (PMID 27582126, 2017). "The concentration of circulating ICAM-1, E-selectin and VCAM-1 was significantly increased in nasopharyngeal carcinoma." (PMID 9888481, 1999).
oral squamous cell carcinoma (6 papers, 2013 to 2025). "The current study explored the combined effect of ICAM-1 gene polymorphisms and exposure to environmental carcinogens on the susceptibility of developing oral squamous cell carcinoma (OSCC) and the clinicopathological characteristics of the tumors." (PMID 24069166, 2013). "Inflammatory mediators including IL-6 and prostaglandin E2 increase ICAM-1 expression in human oral squamous cell carcinoma SCC4 cells in vitro." (PMID 32121422, 2020). "Although many questions remain open, the present data clearly show that butyrate can prevent the cytokine-induced ICAM-1 expression in oral squamous cell carcinoma cells, primary oral epithelial cells and macrophages." (PMID 32121422, 2020). "Our finding that butyrate protects cells from cytokine-induced ICAM-1 expression in oral squamous cell carcinoma cells in vitro does not necessarily explain the in vivo situation." (PMID 32121422, 2020).
pulmonary edema (6 papers, 2014 to 2024). Accumulation of fluid in the lung tissues causing disturbance of the gas exchange that may lead to respiratory failure. "Ropivacaine may be a promising therapeutic agent for treating the cause of pulmonary edema by blocking inflammatory Src signaling, ICAM-1 expression, leukocyte infiltration, and vascular hyperpermeability." (PMID 25097454, 2014). "Pulmonary vascular barrier function, regulated in part by Src kinase-dependent phosphorylation of caveolin-1 and intercellular adhesion molecule-1 (ICAM-1), plays a crucial role in the development of protein-/neutrophil-rich pulmonary edema, the hallmark of ALI." (PMID 25097454, 2014). "In addition, the statistical analysis revealed a significant correlation between ICAM-1 immunoexpression and hemorrhagic alveolar edema (p = 0.034) and marked diffuse alveolar edema (p = 0.034), which support its pivotal role in the molecular mechanisms associated with hypothermia pulmonary edema." (PMID 38611652, 2024). "These values were identical to that for the patients with hydrostatic pulmonary edema in the previous study (median 177 ng/mL), suggesting that the effects of plasma ICAM-1 in the present study on lung injury are minimal in both groups." (PMID 27473050, 2016). "In that study, however, plasma ICAM-1 level is also elevated in the patients with hydrostatic pulmonary edema, who basically have minimal lung injury." (PMID 27473050, 2016). "However, these incidences are very rare in the Tibetan population, which could stem from the elevated levels of pyrogallol in the gut of the Tibetan population, as pyrogallol can suppress ICAM-1 to reduce brain and pulmonary edema." (PMID 38004668, 2023). "Prevotella and Butyrivibrio can produce various SCFAs, which can enter the brain through the blood–brain barrier, downregulate ICAM-1 and VCAM-1 levels, and reduce brain and pulmonary edema." (PMID 38004668, 2023).
sarcoidosis (6 papers, 2013 to 2024). Sarcoidosis is a multisystemic disorder of unknown cause characterized by the formation of immune granulomas in involved organs. "ICAM-1 and leptin were found to be potential markers for the diagnosis of sarcoidosis and differential diagnosis of sarcoidosis and sputum-negative tuberculosis." (PMID 26368286, 2015). "As early as 1993, ICAM-1 was reported to be distributed widely in the vascular endothelium and pulmonary granulation tissue in sarcoidosis patients, consistent with our IHC experimental results." (PMID 26368286, 2015). "The concentrations of serum ICAM-1 and leptin obtained from the ELISA analysis were used to establish ROC curves to identify sarcoidosis (n = 89) and tuberculosis (n = 89)." (PMID 26368286, 2015). "Intercellular Adhesion Molecule 1(ICAM-1) and leptin were screened for differentially expressed proteins relevant to sarcoidosis and tuberculosis." (PMID 26368286, 2015). "We identified 2 differentially expressed proteins, leptin and ICAM-1, for the differential diagnosis of sarcoidosis and sputum-negative tuberculosis." (PMID 26368286, 2015).
sarcoma (6 papers, 2018 to 2024). A usually aggressive malignant neoplasm of the soft tissue or bone. "SJSA-1 was the only pediatric sarcoma cell line with basal ICAM-1 surface expression." (PMID 39723214, 2024). "Regarding its mechanism of action in sarcoma immunotherapy, DAC may induce the upregulation of cancer/testis antigens, MHC molecules, and intracellular cell adhesion molecule-1 (ICAM-1) to promote immune recognition of sarcoma cells." (PMID 29910819, 2018). "The responsiveness of A673 depends on MHC-I and partly ICAM-1, providing a rational to induce MHC-I and ICAM-1 expression to improve the efficacy of adoptive cellular therapies in pediatric sarcomas." (PMID 39723214, 2024). "Among all pediatric sarcoma cell lines tested, A673 EwS cells were the most responsive and the TNF-induced upregulation of MHC-I and ICAM-1 sensitized A673 for the lysis by CHM1319 CD8+ T cells." (PMID 39723214, 2024). "These markers, including ICAM-1, MHC-I and CD83 were variably induced by TNF in the pediatric sarcoma cell lines tested here." (PMID 39723214, 2024). "Applying flow cytometry, immunoblotting, tumor killing and ELISpot assays, we identified TNF and IL-1β to be the strongest inducers of MHC-I, and partly ICAM-1 and CD83 on the majority of pediatric sarcoma cell lines tested." (PMID 39723214, 2024). "Cell‐cell communication analysis showed that SD3 enriched sarcoma cell subtype sarco_2 had low expression of HLA‐DRA, HLA‐E, HLA‐F and HLA‐A, and high expression of ICAM1 and TGFB1." (PMID 39658531, 2024). "We assessed a panel of pediatric sarcoma cell lines, including OS (SJSA-1, U2OS), RMS (RD, RH30) and EwS (A673, TC32, TC71 and SKNMC) for their basal expression of the immunogenic surface markers CD86, CD83, PD-L1, ICAM-1, MHC-I and MHC-II in comparison to healthy donor-derived PBMCs." (PMID 39723214, 2024). "We observed that TNF and IL-1β upregulated MHC class I, ICAM-1 as well as CD83 and PD-L1 on the surface of pediatric sarcoma cell lines, while IL-4, GM-CSF, IL-6 and PGE2 failed to induce respective effects." (PMID 39723214, 2024). "Therefore, TNF is capable of upregulating ICAM-1, MHC-I and, to a lesser extent, CD83 and PD-L1 on multiple pediatric sarcoma cell lines without promoting tumor growth in vitro, and thus was further assessed for its immunostimulatory activity." (PMID 39723214, 2024). "Although pretreatment of pediatric sarcoma cell lines with TNF did not improve unspecific peripheral blood mononuclear cells (PBMCs) cytotoxicity, TNF enhanced specific lysis of 1/3 HLA-A2+ EwS cell lines by CHM1319 CD8+ T cells depending on MHC-I expression and ICAM-1 upregulation." (PMID 39723214, 2024).
systemic inflammatory response syndrome (6 papers, 2013 to 2022). SIRS is a serious condition related to systemic inflammation, organ dysfunction, and organ failure. "The pro-thrombotic state is usually promoted by a high expression of IL-6, followed by ICAM-1 (Intercellular Adhesion Molecule 1) expression and endotheliites, generating a systemic inflammatory response syndrome." (PMID 33806100, 2021). "Serum molecules like IL-1β, IL-6, TNF-α, ICAM-1, and E-selectin were involved in the pathophysiology of systemic inflammatory response syndromes." (PMID 24693284, 2014). "Several experimental data showed that the inhibition of iNOS could be an important therapeutic target to treat septic shock patients and that the adhesion molecules (such as ICAM-1) have been related with the gravity of the sepsis syndrome." (PMID 32082073, 2019). "For example, increases in soluble Icam1 were associated with inflammatory responses, and some clinical studies used soluble Icam1 as a biomarker to classify patients with inflammatory diseases, as well as non-infectious systemic inflammatory responses syndrome." (PMID 36389252, 2022). "Systemic inflammatory response syndrome is characterized by increased serum levels of TNF-α, ICAM-1, E-selectin, IL-1β, and IL-6." (PMID 24369441, 2013).
tuberculosis (6 papers, 1996 to 2024). A chronic, recurrent infection caused by the bacterium Mycobacterium tuberculosis. "Serum levels of s.ICAM-1 and s.VCAM-1 in patients with tuberculosis were higher than those in healthy controls (p < 0.001)." (PMID 18475740, 1996).
ulcer (6 papers, 2015 to 2025). "Among the biomarkers assessed, MMP-9 and CRP demonstrated the highest diagnostic accuracy for DFU detection, while VEGF and ICAM-1 showed promise as early indicators of vascular impairment in pre-ulcer patients." (PMID 40364880, 2025). "Our findings suggest that a combination of MMP-9, CRP, VEGF, and ICAM-1 may serve as an effective biomarker panel for early risk assessment and ulcer progression monitoring." (PMID 40364880, 2025). "ICAM-1 levels were also significantly elevated (control: 120.5 ± 15.4 pg/mL, pre-ulcer: 178.3 ± 20.2 pg/mL, ulcer: 225.6 ± 25.3 pg/mL)." (PMID 40364880, 2025). "Elevated VEGF and ICAM-1 levels in pre-ulcer patients point to early vascular impairment, supporting their potential as early biomarkers." (PMID 40364880, 2025). "VEGF and ICAM-1 levels were significantly elevated in the pre-ulcer group compared to the control group, suggesting early vascular impairment." (PMID 40364880, 2025). "Our study observed significantly elevated levels of VEGF and ICAM-1 in the pre-ulcer group, indicating early vascular impairment preceding ulcer formation." (PMID 40364880, 2025). "Quercetin also generates the expression of P-selectin and intercellular adhesion molecule-1 (ICAM-1) in indomethacin-induced ulcer model in rats." (PMID 38435992, 2024). "Garidisan likely improved the quality of ulcer healing by reducing ICAM-1 expression and modifying the balance of CD3+CD4+ T cells/CD3+CD8+ T cells, Th1/Th2, and their secreted cytokines." (PMID 28928792, 2017). "Further, IL-1β markedly increases infiltration of leucocytes in the superficial portion of scarred mucosa prior to ulcer recurrence, while enhancing ICAM-1 expression." (PMID 26465592, 2015). "VEGF and ICAM-1 were markedly elevated in pre-ulcer patients, indicating early vascular impairment." (PMID 40364880, 2025). "In addition, IL-1β significantly increased intercellular adhesion molecule 1 expression and leucocyte infiltration in the scarred mucosa’s superficial region before ulcer recurrence." (PMID 36712695, 2022).